LEP (leptin)
Diseases named in the same sentence as LEP in open-access papers (continued):
Sharing a sentence is not in itself a finding about the gene and the disease.
Obesity (continued). "Leptin resistance contributes to obesity; targeting leptin signaling may help regulate appetite and improve weight management." (PMID 40013194, 2025). "Leptin resistance manifests as diminished satiety signaling, hyperphagia, and progressive body mass accumulation, serving as key contributors to metabolic dysregulation in obesity." (PMID 40278960, 2025). "Counterintuitively, obesity is characterized by increased leptin production." (PMID 40104296, 2025). "Leptin, conversely, is pro-inflammatory and typically elevated in obesity." (PMID 40519904, 2025). "The incomplete recovery from obesity after treatment with Caf-CNPs, which is indicated by the increased leptin levels and decreased ghrelin levels, could be attributed to the increase in glutamate and GABA, which promotes feeding behavior." (PMID 41309900, 2025). "Adipocytokines such as leptin and adiponectin, which regulate and affect insulin sensitivity and signaling, are deregulated in both psoriasis and obesity, and plasma levels of adiponectin, which has anti-inflammatory action, are decreased in obesity, psoriasis, IR, and T2D." (PMID 40806666, 2025). "Furthermore, it is known that leptin resistance and hypothalamic inflammation both impair the physiological satiety signaling, thus leading to a pathologically elevated set point in obesity." (PMID 40868241, 2025). "At both PPD1 and PPD150, obesity resulted in insulin resistance, impairment of whole-body glucose utilization, increased levels of circulating leptin, and altered profiles of amino acids in plasma, and these effects were attenuated in ewes receiving obesity management during or after gestation." (PMID 41463818, 2025). "The observed results suggest that cord blood appetite hormones (PP, PYY, and leptin) might play a role in the early-life development of obesity." (PMID 41196593, 2025). "However, in obesity, a paradoxical state of leptin resistance often develops, characterized by elevated leptin levels yet impaired biological response, contributing to metabolic dysfunction and insulin resistance." (PMID 40630340, 2025). "Obesity is a state of chronic low-grade inflammation, with adipose tissue acting as an active endocrine organ that produces proinflammatory cytokines such as TNF-α, IL-6, and leptin—all implicated in the pathophysiology of psoriasis." (PMID 41010661, 2025). "However, individuals with obesity exhibit hyperleptinemia and impaired leptin responsiveness, which contribute to greater food intake, reduced energy expenditure, and metabolic dysregulation, exacerbating weight gain and obesity-related complications." (PMID 41016636, 2025). "Both aging and obesity increase serum leptin levels, and beyond this optimal concentration, leptin exerts a destructive effect, while obesity may amplify these detrimental effects." (PMID 39764565, 2025). "Leptin is the best-studied adipokine, discovered in 1994 by cloning the obesity gene in mice." (PMID 40491594, 2025). "In addition, obesity alters adipokine profiles, with increased leptin and decreased adiponectin levels, creating a microenvironment that favors tumor growth." (PMID 41163335, 2025). "The diminishing effectiveness of leptin in suppressing appetite underscores the complex interplay between neuronal pathways and highlights the intricate relationship between adipose tissue and the progression of obesity." (PMID 41373779, 2025). "Moreover, during obesity, adipose tissue–derived hormones such as leptin activate the hypothalamic melanocortin system." (PMID 41457293, 2025). "Next, to investigate whether obesity itself affects AMP expression, we compared AMPexpression between leptin-deficient (Ob/Ob−/−) mice and theirlean wild-type littermates, both groups feeding on a chow diet." (PMID 40760765, 2025).
Obesity (continued). "This review synthesizes available research about the effects of yoga on leptin and adiponectin, examining its potential as a complementary approach to existing obesity treatments, particularly for those who have limited access to conventional treatment options." (PMID 39897330, 2025). "However, its concentrations fall in obesity, while leptin, resistin, and visfatin rise, driving NF-κB and JNK activation in macrophages and parenchymal cells, thereby amplifying systemic IR." (PMID 41463398, 2025). "This study aimed to investigate the gastric expression of FTO and MC4R genes and their association with circulating levels of leptin, adiponectin, and ghrelin in individuals with and without obesity." (PMID 41423640, 2025). "However, leptin resistance, commonly seen in obesity, leads to the impaired regulation of hunger and increased caloric intake, contributing to further weight gain and metabolic dysfunction." (PMID 40362168, 2025). "Additionally, the gut-brain axis has been identified as a new mechanism for improving leptin resistance in obesity." (PMID 39897330, 2025). "However, in obesity, augmented circulating leptin levels frequently fail to exert the typical anorexigenic effects, a phenomenon known as leptin resistance." (PMID 41373779, 2025). "However, obesity-induced leptin resistance disrupts these effects and is often accompanied by brain IR." (PMID 40218960, 2025). "Individuals with obesity often exhibit elevated levels of free, biologically active leptin in the brain, which may increase the likelihood of leptin resistance." (PMID 41439942, 2025). "Leptin resistance, which commonly occurs in obesity, may destabilise respiratory control during sleep, contributing to OSA in some people." (PMID 39932046, 2025). "The visceral adipose tissue is the main contributor to systemic inflammation in obesity, as it can produce and secrete a greater quantity of pro-inflammatory cytokines, such as leptin, adiponectin, interleukin 6, and tumor necrosis factor-α, which is compared to subcutaneous fat." (PMID 40655405, 2025). "Second, the elevation of leptin related to obesity can regulate TSH secretion." (PMID 40379763, 2025). "Evidence suggests that leptin levels are elevated in obesity and kidney injury." (PMID 40703753, 2025). "In humans, individuals with obesity have higher leptin levels compared to lean individuals." (PMID 40522819, 2025). "Finally, obesity-induced hyperleptinemia promotes atherosclerosis by driving selective leptin resistance, preserving harmful vascular effects while dampening metabolic benefits." (PMID 39857433, 2025). "TRZ can mitigate brain leptin resistance, which is the possible link between obesity and AD." (PMID 40498212, 2025). "In other studies, while no formal mediation analysis was conducted, the association between IMF and cognitive function were robust to adjustment for cardiometabolic conditions, including hypertension, diabetes, obesity, measures of inflammation (leptin, adiponectin, IL-6)." (PMID 39974123, 2025). "This shows that CART may contribute to obesity-induced changes in ovarian function, possibly through leptin interaction and gonadotropin control." (PMID 39595164, 2024). "Another study demonstrated that obesity may also contribute to knee OA in young patients due to an elevation in adipokines such as leptin and resistin." (PMID 39229323, 2024). "Leptin and adiponectin demonstrate distinct clinical utility in obesity-related pathologies." (PMID 39795949, 2024). "Initially, a diet low in energy density due to fat restrictions may reduce serum leptin levels, leading to metabolic adaptations that could contribute to obesity and leptin resistance later in life." (PMID 39495734, 2024). "They propose that strategies aimed at partially reducing circulating leptin may represent a promising approach for the treatment of obesity and diabetes." (PMID 39872218, 2024). "Elevated levels of leptin often characterize obesity due to increased fat mass." (PMID 39411599, 2024).
Obesity (continued). "Considering the high prevalence of metabolic syndrome in women with PCOS and the correlation between reduced leptin levels, obesity, and metabolic syndrome, green tea could be considered a part of the treatment strategy." (PMID 38737668, 2024). "In addition, leptin is selectively resistant in obesity, resulting in a reduced appetite-reducing effect but a preserved SNS activity response in the kidneys." (PMID 39217385, 2024). "The consequences of hippocampal leptin resistance extend beyond metabolic dysregulation to encompass profound effects on learning, memory and reward processing, which in turn can exacerbate overeating and obesity in rodents and humans." (PMID 39594988, 2024). "Leptin is another relevant factor in this metabolic cascade, since, produced in excess by the adipose tissue in subjects with overweight/obesity, it affects FSH and LH pituitary release and pulsatility while also maintaining low grade inflammation, increasing ROS and decreasing sperm quality." (PMID 37697017, 2024). "However, in the context of obesity and leptin resistance with the activation of the TLR4/Myd88/NFkB axis, an enhanced SOCS3 expression occurs, causing a pathologic leptin signaling inhibition." (PMID 38933275, 2024). "Obesity clearly interferes with the ability of leptin to fulfill its usual physiological role." (PMID 38872138, 2024). "In addition to insulin, the transport of the hormone leptin across the BBB is also altered in obesity." (PMID 38678254, 2024). "Moreover, the shift towards M1 macrophage dominance is further driven by the altered adipokine profile in obesity, particularly the elevated levels of leptin and reduced levels of adiponectin, both of which influence macrophage polarization." (PMID 39273478, 2024). "Leptin is secreted by the adipose tissue and has been extensively studied in obesity, where leptin can be highly produced and negatively contribute to the inflammation of the adipose tissue, further impairing the normal function of the adipose tissue in obese patients." (PMID 38302474, 2024). "For the first time, our data demonstrates that inhibition of autophagy and OXPHOS can avoid the migratory capacity of highly invasive cells exposed to leptin and contributes to underscoring the importance of metabolic changes and their modulators, like leptin or autophagy, in obesity-related cancer." (PMID 38228661, 2024). "Obesity is characterized by alterations in hormone levels, such as leptin and adiponectin." (PMID 39118100, 2024). "However, obesity is often coupled with both increased leptin levels and leptin resistance, which diminishes its effectiveness in promoting weight loss." (PMID 38131197, 2024). "The inflammatory status in obesity may, at least in part, result from the activation of the cells of the immune system by leptin, including monocytes, T lymphocytes, and natural killer (NK) cells." (PMID 38397015, 2024). "Moreover, the genetic aspect of obesity, particularly the role of specific polymorphisms in genes like obesity-associated (FTO), leptin (LEP), leptin receptor (LEPR), and melanocortin 4 receptor (MC4R) genes, has been extensively studied." (PMID 38398881, 2024). "However, states of hyperleptinemia and related leptin resistance are characteristic of long-standing obesity, due to the direct proportion of the amount of adipose tissue and circulating leptin concentrations." (PMID 38613104, 2024). "Only then might the great potential for leptin’s discovery to illuminate the pathophysiology and treatment of obesity be fulfilled." (PMID 38165042, 2024). "Our previous study indicated that obesity altered the methylation status of Leptin, which might play a role in the metabolic disorders of female offspring." (PMID 39642055, 2024). "Consequently, it is established that the alterations relating to leptin levels, observed in obesity, negatively influence not only endometrial receptivity but also implantation and therefore lead to lower fertility." (PMID 38999965, 2024).
Obesity (continued). "Likewise, hypothalamic dysfunction, parasympathetic-sympathetic imbalance, impaired release of neurotransmitters, such as noradrenaline or dopamine, and increased circulating leptin levels, have been addressed as a potential link between migraine and obesity." (PMID 38347465, 2024). "In fact, studies have demonstrated that high leptin levels are related to cardiometabolic dysfunction in both the adult and pediatric populations, highlighting the importance of this marker in obesity and its related diseases." (PMID 39457561, 2024). "Furthermore, SERT KO mice develop a metabolic syndrome-like phenotype that includes increased leptin, glucose intolerance, insulin resistance, obesity, and hepatic steatosis as they age." (PMID 38674044, 2024). "Regarding obesity, they reported some effects of adiponectin and leptin in cancer progression (the levels of these two adipokines are inversely and directly related to obesity) and they analyzed the role of a pro-inflammatory cytokine such as IL-6 and TNF-α in cancer development." (PMID 39410050, 2024). "Obesity could increase leptin expression by downregulating tumor suppressor p16INK4A expression, which promoted the precancerous development of BC." (PMID 38405061, 2024). "The excess visceral adiposity, typical of obesity, is responsible for increasing the number of molecules that induce cancer pathogenesis, such as leptin, resistin, and other adipokines, in addition to pro-inflammatory cytokines such as IL-1, IL-6, IL -8, and TNF-α, elevating the risk of neoplasms." (PMID 39042663, 2024). "Leptin is produced in proportion to the fat mass; therefore, its expression is elevated in obesity." (PMID 38255203, 2024). "By using mice lacking leptin, deficient in leptin receptors, and those with diet-induced obesity, researchers illustrated heightened levels of macrophage markers in white adipose tissue (WAT) compared to their respective control groups." (PMID 39457523, 2024). "The paradoxical effect of obesity on cancer outcomes could be influenced by the pro-inflammatory effect of leptin, potentially enhancing the efficacy of immune checkpoint inhibitors." (PMID 38255203, 2024). "A potential explanation might be in the different central actions of insulin and possibly leptin in patients with obesity." (PMID 39000449, 2024). "Stocker C.J., Cawthorne M.A. The influence of leptin on early life programmingof obesity." (PMID 38952707, 2024). "However, the clinical application of leptin therapy presents significant challenges, particularly due to the phenomenon of leptin resistance in obesity." (PMID 39594988, 2024). "As was shown from studies in high-fat diet fed mice, in obesity, important mediators in the observed leptin resistance in AgRP neurons are JNK, NF-kB, suppressor of cytokine signaling 3 (SOSC3), protein tyrosine phosphatase 1B (PTP1B, also known as polypyrimidine tract binding protein 1), and PKC." (PMID 39728000, 2024). "Obesity induces metabolic disorders, chronic low-grade inflammatory status and hormone alterations (e.g., higher levels of leptin, insulin, androgen, estrogen), which could further impair ovarian folliculogenesis." (PMID 38455649, 2024). "In addition to the chronic inflammatory state of obesity, the adipokine leptin, which regulates energy balance and metabolism in adipose tissue, has been implicated in developing psoriasis." (PMID 38988999, 2024). "Additionally, obesity-related hormonal imbalances, such as altered levels of leptin and ghrelin, disrupt sleep by affecting appetite regulation and metabolic processes." (PMID 39525192, 2024). "The findings from these animal studies suggest that maintaining low leptin levels may be beneficial for management of obesity and diabetes, although its effectiveness needs to be clinically verified." (PMID 40302954, 2024).
Obesity (continued). "As the kidney has receptors for leptin, it may be related to hypertension developing in obesity, ability to interact with the sympathetic nervous system, and is metabolized in the kidney." (PMID 39199293, 2024). "Overcoming obesity-induced leptin resistance has been a challenge for a long time." (PMID 38561362, 2024). "However, excessive leptin production such as that seen in severe obesity conditions would contribute to the cardiac hypertrophic and remodelling processes." (PMID 38256208, 2024). "When the P38 MAPK signaling pathway is activated, leptin production is inhibited, which may lead to fat accumulation and obesity." (PMID 39539361, 2024). "However, contrary to this finding, there are also studies showing that common polymorphisms in the LEP gene and the leptin receptor (LEPR) gene play an important role in obesity and obesity-related metabolic biomarkers." (PMID 39594868, 2024). "Functional deficiencies in leptin and ADCY3 disrupt feeding control and promote obesity and T2D." (PMID 39352389, 2024). "Serum leptin increased with BMI and showed the highest levels in severe obesity." (PMID 39310722, 2024). "Consequently, differences in BAT thermogenesis do not seem to significantly contribute to the observed effects of leptin during lactation on later body weight, namely resistance to the development of overweight/obesity." (PMID 38786092, 2024). "This mouse model could also be used to test the efficacy of drugs targeting the signaling pathways altered by obesity, including insulin, leptin, and free fatty acid." (PMID 39201703, 2024). "The underlying mechanism, especially its association with indicators reflecting obesity in vivo, such as lipids, serum leptin, adiponectin and their receptors, has not yet been fully evaluated." (PMID 39183988, 2024). "Common obesity is characterized by leptin resistance and hyperleptinemia." (PMID 39125635, 2024). "The interaction between zinc metabolism and leptin may shed light on the link between the zinc status and obesity." (PMID 38391792, 2024). "Furthermore, KA decreased the adipose tissue size and downregulated the expression of genes related to insulin resistance in obesity, including leptin, PPARγ, and adiponectin." (PMID 38655315, 2024). "These evidences indicated that adipocyte ESRRA deficiency modulates leptin level without disturbing general metabolism in the context of HFD-induced obesity." (PMID 38704393, 2024). "While most cases of obesity are associated with hypothalamic leptin resistance, the peripheral effects of leptin signaling or leptin resistance in obesity are not fully elucidated." (PMID 38397015, 2024). "However, in the context of conventional obesity, administration of additional leptin is largely ineffective." (PMID 39872218, 2024). "Similarly, as leptin levels are influenced by obesity-induced inflammation, over-expressed leptin was positively correlated with the accumulation of MDSCs in mice on a high-fat diet." (PMID 39518420, 2024). "Most of the genes involved in the VUS were obesity-related ciliopathies (16/28, 57%), followed by the cell-signaling regulation genes (6/28, 21%), leptin signaling pathway (3/28, 11%), and unknown mechanisms (3/28, 11%)." (PMID 38674329, 2024). "Furthermore, research has shown that both the synthesis of leptin and inflammatory cytokines are elevated in obesity." (PMID 39055496, 2024). "Adipokines such as leptin and proinflammatory cytokines such as TNFα, IL-6 and IL-18 are involved in the pathogenesis of obesity-related insulin resistance in women with PCOS but seem also to be directly implicated in the pathogenesis of ovarian and adrenal dysfunction." (PMID 38540265, 2024). "Therefore, our findings concerning CRP and leptin levels reinforce the idea that obesity-related inflammation begins early in childhood." (PMID 39768291, 2024). "The resulting hyperinsulinemia could, in turn, exacerbate obesity and further increase leptin levels and gene expression in white adipose tissue." (PMID 39684379, 2024).